CD24 (CD24 molecule)
Diseases named in the same sentence as CD24 in open-access papers (continued):
Sharing a sentence is not in itself a finding about the gene and the disease.
colon carcinoma (46 papers, 2008 to 2025). "Blocking the CD24–Siglec-10 anti-phagocytic axis effectively activates macrophage-mediated phagocytosis in the MC38 colon cancer model." (PMID 40873588, 2025). "In colon cancer xenograft mouse models, treatment with anti-CD24 antibodies effectively suppressed the tumor growth." (PMID 40873588, 2025). "We showed that continuous culture for three generations of colon tumour spheroid led to the stem marker CD24 gradually increasing." (PMID 36612229, 2022). "Colon cancer stem cells can express specific surface markers such as CD24, CD44 and CD133, which are highly resistant to radiotherapy and chemotherapy." (PMID 35242031, 2022). "Among them, CD24 was shown to play an important role in clustering/connecting the colon CSCs and contribute to the metastatic potential of colon cancer." (PMID 36612229, 2022). "A total of 511 patients with colon cancer were included in 4 studies to evaluate the correlation between the expression of CD24 in colon cancer and tumor diameter, including 174 patients with tumor diameter > 5 cm and 337 patients with tumor diameter ≤ 5 cm." (PMID 35938128, 2022). "To further verify the effect of TP5 on colon cancer stem cells, we used flow cytometry to detect the expression of cancer stem cell markers CD24, CD44 and CD133, which are surface markers that can be specifically expressed by colon cancer stem cells." (PMID 35242031, 2022). "More recently, it was shown that single CD133+/CD24+ colon cancer stem cells can self-renew and reconstitute a complete and differentiated carcinoma." (PMID 29652830, 2018). "Previous reports also showed that increased CD24 expression reverted to a normal level after short (72 h) and long (6 months) exposure to celecoxib in colon cancer." (PMID 28611669, 2017). "Instead, we further defined a subpopulation of the CD24+ cells as the potential colon CSCs: CD133+CD24lo colon cancer cells." (PMID 27659530, 2016). "Further, as CD24 as well as CD44-positive subpopulations from colon cancer cell-lines have been reported to possess stem cell-like properties, we examined effects on this population in SW480 and HT29 cells, using flow cytometry analysis." (PMID 27283988, 2016). "The cell surface proteins CD133, CD24 and CD44 are putative markers for cancer stem cell populations in colon cancer, associated with aggressive cancer types and poor prognosis." (PMID 24760019, 2014). "We found that CD44 and CD24 were present abundantly in human colon cancer tissues, and conversely, both of them were weakly detectable in human adjacent noncancerous colon tissues." (PMID 24696849, 2014). "Accordingly, CD133+/CD24+ marked clonogenic TICs derived from single colon carcinoma cells in spheroid cultures or limiting dilutions." (PMID 23150174, 2013). "A small subset of CD133-positive colon carcinoma cells additionally expressed CD24, CD44 or CDCP1, so that a correlation in antigen expression can be assumed." (PMID 22433494, 2012). "CD24 is also expressed in spheroid cultures of colon cancer CSCs, suggesting that it may serve as a marker for colon cancer CSC populations." (PMID 40486886, 2025). "CD24 is indeed an important biomarker to maintain stemness at least in colon cancer." (PMID 36612229, 2022). "Indeed, treatment with CD24 monoclonal antibody reduced tumor burden in mice harboring bladder, pancreatic, lung, ovarian, and colon cancer." (PMID 35884847, 2022). "Ultimately, based on our MCIA, we identified CD15, CD104 (Integrin-β4), CD324 (E-cadherin), CD326 (EpCAM), and CD49f as biomarkers for colon cancer and CD24, CD26 (DPP4), CD106 (VCAM1), TIM-1, SSEA-3 (B3GALT5), SSEA-4 (TMCC1), TRA-1-60-R (PODXL) and EGFR for renal cancer." (PMID 36221114, 2022).
colon carcinoma (continued). "Besides Sox2 and ALDH, expression of several other surface proteins, such as CD44, CD133, Lgr5, CD24, EpCAM and ABCG2, has been associated with stemness features in the context of colon cancer." (PMID 32927726, 2020). "In this study, we observed that CD24 is highly expressed on human colon carcinoma cells." (PMID 27659530, 2016). "However, our observation does not necessarily contradict the previous observation that CD24+ tumor cells are subsets of colorectal CSCs since the 5-FU-resistant human colon carcinoma cells are all CD24+." (PMID 27659530, 2016). "We had previously shown that treatment of pancreatic and colon cancer cell lines with anti-CD24 monoclonal antibodies (MAbs) or CD24 downregulation using short hairpin (sh)RNA effectively inhibited cell proliferation in vitro and retarded tumorigenicity in xenografted nude mice." (PMID 26394139, 2015). "Using immunohistochemistry, we found that CD44 (95%) and CD24 (91%) were expressed abundantly in human colon cancer glandular tissues, whereas CD44 (35%) and CD24 (20%) were undetected or weakly detectable in human adjacent noncancerous colon glandular tissues." (PMID 24696849, 2014). "Isolation of CSCs from colon carcinomas can be accomplished by selection of a subpopulation of tumor cells based on expression of one or multiple cell surface markers associated with cancer stemness, like CD133, CD44, CD24, CD29, CD166 and Lgr5." (PMID 21311095, 2010). "To further verify whether TP5 promotes the antitumor effect of OXA by inhibiting colon cancer stem cells, we measured the expression of cancer stem cell markers CD24 and CD44 by flow cytometry after TP5 and OXA were co-administered to colon cancer HCT116 cells for 24 h." (PMID 35242031, 2022). "However, we also observed that although CD24 is highly expressed in the human colon carcinoma cell lines, a small population (0.12-1.66%) of human colon carcinoma cells express low intensity of CD24, suggesting the heterogeneity of CD24-expressing cells in human colon carcinoma cells." (PMID 27659530, 2016). "Therefore, CD44 and CD24 could be used as markers for selecting colon cancer stem cells from SW480 cells, LOVO cells, and HCT116 cells by MACS." (PMID 24696849, 2014). "Targeting phagocytosis checkpoints such as CD47-SIRPα, CD24-Siglec-10, MHC-LILRB1, PD1-PDL1 and thereby modulating immune escape in colon cancer cells has also been demonstrated." (PMID 40873588, 2025). "To validate our data analysis results, we extracted total RNA from patient colon cancer tissue and corresponding normal colon epithelial tissue and measured the mRNA expression levels of TIMP1, VEGFA, MYC, MSLN, EPHA2, ABHD2, and CD24." (PMID 38773226, 2024). "In contrast, downregulation of CD24 inhibits the interaction between CD24 and FAK and prevents the proliferation and invasion of colon cancer cells, suggesting that curcumin has preventative and therapeutic effects on colon cancer." (PMID 36362132, 2022). "For colon cancer, identified biomarkers are CD15, CD104, CD324, CD326, CD49f, and for renal cancer, CD24, CD26, CD106 (VCAM1), EGFR, SSEA-3 (B3GALT5), SSEA-4 (TMCC1), TIM1 (HAVCR1), and TRA-1-60R (PODXL)." (PMID 36221114, 2022). "Regarding colon cancer network, genes including NME2, ATP1A1, CD24 and IFI6 showed the most connectivity." (PMID 29118934, 2017). "We demonstrated enrichment of CD133, CD44, and CD24-positive cell populations and increased sphere-forming capacity following cumulative exposure to NNK in colon cancer cells." (PMID 26992205, 2016). "CD24 is one of the genes whose expression level is lower in the CD133+ and 5-FU-resistant colon cancer cells as compared to CD133+ and 5-FU-sensitive colon cancer cells." (PMID 27659530, 2016). "In the present study, we have investigated the differences in the expression patterns of CD133, CD24, CD44 and EGFR in three colon cancer cell-lines; HT-29, HCT116 and DLD-1." (PMID 24760019, 2014).
colon carcinoma (continued). "Our study characterized a large panel of colon carcinoma cell lines and their corresponding xenografts, showing significantly reduced expression of the cell surface markers CD133, CD44, CD24, CDCP1 and CXCR4 in vivo." (PMID 22433494, 2012). "We characterized a panel of fourteen human colon carcinoma cell lines and their corresponding xenografts for the surface expression of potential stem cell markers CD133, CD24, CD44, CDCP1 and CXCR4." (PMID 22433494, 2012). "Our data revealed correlations in the expression of surface markers CD44 and CD24 as well as CD44 and CDCP1 and strongly suggest that CD133 is a stem cell marker within our colon carcinoma panel." (PMID 22433494, 2012). "Nevertheless, in our study, we found that the suppression of G13D mutation promoted major stem markers like CD133, Lgr5, and TGF-β but not others like CD44 and CD24, which were reported as common and important biomarkers for colon cancer by us and others." (PMID 36386200, 2022). "For CSCs, there is no unique biomarker to identify them, for instance, in colon cancer, the most popular biomarkers are some surface adhesion molecules like CD24, CD44, and CD133." (PMID 36386200, 2022). "However, OXA also reduced the expression of CD24 and CD44, which are specific surface markers for colon cancer stem cells, while TP5 mildly enabled OXA to exert an inhibitory effect on stem cell stemness." (PMID 35242031, 2022). "Secondly, CD24, CD44 and CD133 are specific surface markers that can be expressed by colon cancer stem cells; ALDH1, OCT4, SOX2 and Nanog are all markers of stemness status of cancer stem cells, which are important for maintaining the nature and drug resistance of cancer stem cells." (PMID 35242031, 2022). "In fact, it was shown that colon cancer cell lines contain cancer stem cell populations that can be enriched by the use of an in vitro, Matrigel-based differentiation assay together with selection for the expression of CD44 and CD24 cell surface markers." (PMID 29652830, 2018). "Further analysis of cell surface CD24 protein levels validated our gene-wide gene expression analysis and revealed that 5-FU treatment enriched not only CD133+ but also CD24lo subsets of human colon carcinoma cells." (PMID 27659530, 2016). "Moreover, we determined CD44/CD24 expression for breast and CD44/CD133/CD326 expression for colon cancer cell lines to study the proportion of cancer cells with a CSC phenotype in the different subpopulations." (PMID 26752044, 2016). "We further probed the expression of Nodal ligand and its receptors in CD44-negative as well as CD24-positive and -negative colon cancer cells." (PMID 24696849, 2014). "Using MACS, we selected CD44- and CD24-positive and -negative colon cancer cells from SW480 cells, LOVO cells, and HCT116 cells." (PMID 24696849, 2014). "It has been suggested that CD44, CD24, and CD133 are hallmarks for colon cancer stem cells (CCSCs)." (PMID 24696849, 2014). "Significantly, we revealed that Nodal transcript and protein were absent in CD44- and CD24-negative colon cancer cells, whereas it is present in CCSCs, implicating that Nodal is required for maintaining stemness of colon cancer stem cell." (PMID 24696849, 2014). "In summary, the three colon cancer cell lines had a varying expression of CD133, CD44 and CD24." (PMID 24760019, 2014). "In the present study, we found that TP5 can directly inhibit cultured colon cancer stem cells in medium without serum, and reduce the expression of cancer stem cell markers: CD44, CD24 and CD133, and stem-cell related genes: ALDH2, SOX2, OCT4 and Nanog." (PMID 35242031, 2022). "Treatment of human colon carcinoma cells with high dose of 5-FU did not increase CD133 expression level or decrease CD24 expression level, suggesting that 5-FU does not regulate CD133 and CD24 expression." (PMID 27659530, 2016).
melanoma (46 papers, 2008 to 2026). A malignant, usually aggressive tumor composed of atypical, neoplastic melanocytes. "CD24 has been identified as a Siglec-10 ligand in melanoma and is associated with poor prognoses and enhanced tumor growth and metastasis in vivo." (PMID 40885395, 2025). "Further investigations are needed in support of our findings and to determine the precise mechanism underlying the survival and proliferation of CD24+veAnnexin+ve FSClowSSChigh melanoma cells." (PMID 39136818, 2025). "Validation using melanoma data from TIDE revealed that key CSS-associated molecules (CD24, HSPB1, SLC25A5) profoundly influenced immunotherapy outcomes." (PMID 40777020, 2025). "CD24 and Sox2 have been implicated in adaptive therapy resistance in melanoma." (PMID 40754577, 2025). "In melanoma, the increased expression of CD24 was associated with resistance to BRAF inhibitors." (PMID 36013184, 2022). "In melanoma, LKB1 loss display that it may promote melanoma invasion by disrupting directional migration toward extracellular matrix or by inducing the SRC family kinase (SFK)-dependent expansion of a CD24+ tumor subpopulation." (PMID 29371951, 2017). "In this review, we synthesize evidence indicating that CD24 is both a tumour-intrinsic and tumour-extrinsic regulator in melanoma." (PMID 42126185, 2026). "TGFβ is an inducer of the EMT-like as well as amoeboid-like state in melanoma, so reduction of the CD24+ and increase in the CD271+ populations in response to TGFβ further supports the non-EMT-like status of the CD24+ cells." (PMID 40754577, 2025). "Knowles and co-authors identified a rare CD24+CD271+ subpopulation within melanoma with heightened stem-like properties, including lineage plasticity and self-renewal." (PMID 40867277, 2025). "Using the epithelial tumour CSC marker CD24 alongside the melanoma CSC marker CD271, we have identified a minority CSC sub-population that exhibits enhanced self-renewal and lineage plasticity." (PMID 40754577, 2025). "The Broad Institute melanoma immunotherapy scRNAseq dataset had one tumour out of 14 containing CD24+ cells." (PMID 40754577, 2025). "Previous findings have shown that CD24 expression in primary melanoma is one of the most predictive markers for metastatic disease." (PMID 40754577, 2025). "Survival analysis of melanoma patients, stratified by CD24 mRNA expression levels (top 5 percentile), shows a trend towards unfavorable outcome in patients with very high CD24 expression (log rank p-value 0.02)." (PMID 39136818, 2025). "Alongside Sox2, JAK (up in the CD24+CD271+ and CD24+CD271− sub-populations) has been associated with melanoma immunotherapy resistance." (PMID 40754577, 2025). "IHC showed that CD24+ EVs were detected in the serum of melanoma patients and BC, and it is also known as the heat-stable antigen CD24." (PMID 40297849, 2025). "Both CD24+ve and CD24−ve subpopulations are considered to possess self-renewal properties in various cancer types, including melanoma, and are therefore widely used as a marker to isolate cancer stem cells." (PMID 39136818, 2025). "Only 3 (10%) tumours had evidence of CD24+CD271+ melanoma cells and, interestingly, CD24+CD271− melanoma cells were also restricted to these same 3 tumours." (PMID 40754577, 2025). "We identified a CD24+CD271+ minority sub-population in melanoma that possesses the stem cell characteristics of lineage plasticity and self-renewal." (PMID 40754577, 2025). "Often MUCs have been identified to carry these ligands; however, in melanoma also, CD24, CD43, and the gangliosides GD2, GD3, and GM3 are sialylated." (PMID 40885395, 2025). "Additional clinical trials evaluating agents that target the CD24 immune checkpoint in patients with melanoma or advanced solid tumors have been registered (NCT04552704, NCT04060407)." (PMID 36013184, 2022). "CD24 was shown to be important marker of poor prognosis or marker for tumorigenesis in malignant melanoma." (PMID 33196458, 2020).
melanoma (continued). "Potentially, CD24 expression was mediated by STAT3-dependent /SOX2-mediated pathways that was correlated with adaptive resistance toward targeted therapy in melanoma." (PMID 33196458, 2020). "Studies have indicated that attenuated LM was able to induce antitumor immunity against a number of tumor associated antigens such as hepatic cancer stem cell biomarker CD24 and malignant melanoma MIA gene." (PMID 28706878, 2017). "The only distinct and clearly separable subpopulation of melanoma cells (up to 40% of all cells) co-expressed EPO-R and CD24, and was found to contain melanoma-initiating cells when injected into NSG mice." (PMID 24489649, 2014). "In contrast to other antigens, the EPO-R was found to be expressed on a distinct subpopulation of melanoma cells co-expressing CD24." (PMID 24489649, 2014). "In melanoma, CD24 is part of the CD44+CD133+CD24+ stem cell-like immunophenotype in B16-F10 mouse melanoma cells and is upregulated in these cells during in vivo tumor formation." (PMID 23166783, 2012). "Our present finding furthers this notion and suggests that constitutive or forced expression of GDF3 in melanoma cells links the high CD24 expression accelerating tumor growth." (PMID 20950440, 2010). "We summarize the structure, glycosylation and regulation of CD24, then discuss its role in melanoma, supporting phenotypic plasticity, sustaining stem-like populations and promoting resistance to BRAF-targeted and cytotoxic therapies through SOX2/STAT3-linked programmes." (PMID 42126185, 2026). "We then examine the CD24-Siglec-10 axis as an innate immune checkpoint that suppresses macrophage and dendritic cell function, promotes immune-excluded 'cold' tumour microenvironments and may shape responses to immunotherapy among CD24+ melanoma cells." (PMID 42126185, 2026). "Moreover, melanoma patients receiving immune checkpoint blockade (ICB) therapy with high expression of CD24, HSPB1, and SLC25A5 also had a poor prognosis." (PMID 40777020, 2025). "Therefore, we conclude CD24 as a novel cell surface marker for anastasis in malignant melanoma cells." (PMID 39136818, 2025). "Based on our unexpected observation of the cell surface expression of CD24, we here investigated whether CD24 expression is associated with the reversal of apoptosis using B16-F10 and YUMM 5.2 cells as melanoma cellular models." (PMID 39136818, 2025). "We investigated whether a CD24+CD271+ CSC sub-population exists in human primary melanoma specimens." (PMID 40754577, 2025). "A pro-metastatic CD24+ sub-population has also been characterised in a mouse model of melanoma." (PMID 40754577, 2025). "We report CD24 as the first novel cell surface marker for anastasis in melanoma cells." (PMID 39136818, 2025). "Increased CD24 expression was shown to be associated with decreased sensitivity to BRAFi in resistant melanoma cells, while elevated ALCAM levels were observed in the vemurafenib-resistant melanoma cell line." (PMID 39175042, 2024). "Since CD24 expression can be induced by SOX2 in melanoma cells, we asked whether CD24 might be regulated by SOX2 in ECs as well." (PMID 34293822, 2022). "Additionally, SOX2 has already been shown to induce CD24 expression in a melanoma cell or a murine model." (PMID 34293822, 2022). "Additionally, CD24 expression analysis allowed for the prediction of metastasis in malignant melanoma." (PMID 34360811, 2021). "Monitored CSCs-surface markers, associated with stemness, resistance, tumor progression, adhesion, and invasion, were find to be not significantly up- or downregulated and TNFα makes cells only slightly more positive for these markers (CD166 and CD271 in melanoma; CD24 and CD26 in carcinoma)." (PMID 33957885, 2021). "This suggested the melanoma stem-like characteristics in drug-selected cells as CD13+CD24+." (PMID 33196458, 2020). "Interestingly, in all samples analyzed, CD24 was expressed on a subpopulation of melanoma cells that also co-expressed the EPO-R." (PMID 24489649, 2014).